RNU7-174P (RNA, U7 small nuclear 174 pseudogene)
Gene: Small nuclear RNA gene on chromosome 8 (80,560,567 to 80,560,625, forward strand). Ensembl gene ENSG00000252057.
Homologues: Orthologues: macaque U7 (97% identical). Paralogues in human: RNU7-82P (90% identical), RNU7-97P (90% identical), RNU7-35P (85% identical), RNU7-88P (85% identical), RNU7-104P (83% identical), RNU7-124P (83% identical), RNU7-167P (83% identical), RNU7-28P (83% identical), RNU7-40P (83% identical), RNU7-60P (83% identical), RNU7-69P (83% identical), RNU7-7P (83% identical), and 142 more.